SIRT1 (sirtuin 1)
Diseases named in the same sentence as SIRT1 in open-access papers (continued):
Sharing a sentence is not in itself a finding about the gene and the disease.
diabetic cardiomyopathy (continued). "Fang and Ma showed that SIRT1 expression was reduced in a mouse model of diabetic cardiomyopathy resulting in both compromised insulin signaling and mitochondrial dynamic abnormity." (PMID 31076562, 2019). "Generally, protective effects of SIRT1 are shown to be correlated with alleviation of ER stress, such as those in diabetic cardiomyopathy." (PMID 30918470, 2019). "LncRNA HOTAIR functions as a ceRNA to upregulate Sirtuin 1 (SIRT1) by sponging miR-34a in diabetic cardiomyopathy." (PMID 31684870, 2019). "We examined the effects of Sn(tin)-mesoporphyrin (SnMP), which is an inhibitor of HO activity, the HO-1 inducer cobalt protoporphyrin (CoPP), and the SIRT1 inhibitor (EX-527) on diabetic cardiomyopathy." (PMID 31100876, 2019). "We have previously shown the beneficial effect of caloric restriction (CR) on diabetic cardiomyopathy through intracellular signaling pathways involving the SIRT1–PGC-1α axis." (PMID 31100876, 2019). "The protective role of SIRT1 has been proven in multiple pathological conditions including atherosclerosis, diabetic cardiomyopathy, and cardiomyopathy." (PMID 30918470, 2019). "Application of Sirtuin 1 activator resveratrol enhanced the expression and activity of SERCa2a, which attenuated depressed contractile function in both a mouse model of diabetic cardiomyopathy and a rat model of hypertrophy." (PMID 31091723, 2019). "The expression of SIRT1 was shown to be reduced in a mouse model of diabetic cardiomyopathy and resulted in both compromised insulin signaling and mitochondrial dynamic abnormity." (PMID 30071860, 2018). "Whereas deletion of SIRT1 expression in the heart contributed to phenotypes resembling diabetic cardiomyopathy in vivo and to mitochondrial dysfunction through PGC1-α in vitro." (PMID 30071860, 2018). "It has been reported that resveratrol has the ability to stimulate SIRT1 and protects against diabetic cardiomyopathy in experimental animals." (PMID 26489513, 2015). "Previous studies have employed liposomal nanotechnology to deliver Ginkgo flavone glycosides, demonstrating that this approach can activate SIRT1 and alleviate the pathological processes of diabetic cardiomyopathy by modulating oxidative stress and inflammatory responses." (PMID 40958892, 2025). "Furthermore, melatonin was found to relieve oxidative stress and ER stress-induced apoptosis in diabetic cardiomyopathy through SIRT1, AMPK, and PGC1α activation." (PMID 39857351, 2024). "In addition, SIRT1 can also promote the expression of various antioxidant enzymes to combat oxidative stress responses in diabetic cardiomyopathy, such as manganese superoxide dismutase (MnSOD), through deacetylation of FOXO3a." (PMID 35739982, 2022). "On the other hand, SIRT1 and Rab7 siRNA prevented the resveratrol improvement of autophagy flux and cardiac function, suggesting that resveratrol participates in the improvement of diabetic cardiomyopathy through SIRT1-FOXO1-Rab7-autophagy pathway." (PMID 35909524, 2022). "Moreover, SIRT1 activation by intraperitoneal injection of RSV (25 mg/kg) alleviated cardiac dysfunction via improving mitochondrial function in diabetic cardiomyopathy mice." (PMID 36143977, 2022). "Allisartan isoproxil, a blocker of the angiotensin II receptor that is used to reduce the risk of heart disease, mitigates diabetes-induced OS and inflammation by upregulating Sirt1/Nrf2/HO-1 signal and inhibiting the NF-κB activation, respectively, in diabetic cardiomyopathy (DCM) rats." (PMID 35103095, 2022). "Emerging evidence suggests the role of SIRT1-mediated autophagy in diabetic cardiomyopathy." (PMID 35909524, 2022). "In addition, rosmarinic acid has been shown to improve cardiac dysfunction and mitochondrial damage in mice with diabetic cardiomyopathy by activating the SIRT1/PGC-1α signaling pathway." (PMID 34484404, 2021).
diabetic cardiomyopathy (continued). "Consequently, we concluded that BAK ameliorated diabetic cardiomyopathy by reducing myocardial oxidative damage in a SIRT1/Nrf2 signaling-dependent pathway." (PMID 33062139, 2020). "In summary, these data indicated that Nrf2 might function downstream of SIRT1 signaling in mediating the cardioprotective actions of BAK against diabetic cardiomyopathy." (PMID 33062139, 2020). "However, while the antidiabetic effect of SIRT1 has been extensively researched, there is few data concerning the role of SIRT1 in the pathogenesis of diabetic cardiomyopathy (DCM)." (PMID 32486051, 2020). "PHL is a promising natural product that could protect against diabetic cardiomyopathy with its therapeutic target being SIRT1." (PMID 31076562, 2019). "Deletion of cardiac SIRT1 expression contributed to phenotypes resembling diabetic cardiomyopathy." (PMID 31076562, 2019). "SIRT1 is found in the nucleus and cytoplasm, and is considered to be a potential target for treatment of human pathologies, including cardiovascular disease, like diabetic cardiomyopathy." (PMID 31076562, 2019). "Thus Sirt1 activators such as resveratrol can used as CR mimetics to reduce diabetic cardiomyopathy." (PMID 30071860, 2018). "Resveratrol improves cardiac dysfunction and remodelling and attenuates cardiomyocyte apoptosis and oxidative stress injury in diabetic mice, associated with the regulation of autophagic flux through SIRT1/FOXO1/Rab7 axis, which suggests a therapeutic strategy for diabetic cardiomyopathy." (PMID 24889822, 2014). "SIRT1 could decrease oxidative stress in diabetic cardiomyopathy." (PMID 37055837, 2023). "Therefore, it is of great interest to probe whether SIRT1/Nrf2 signaling plays a vital role in the amelioration actions of BAK against diabetic cardiomyopathy." (PMID 33062139, 2020). "Besides, SIRT1 directly deacetylated FOXO3a and promoted the expression of MnSOD and catalase that are involved in stress resistance, which in turn attenuated oxidative stress in diabetic cardiomyopathy and nephropathy." (PMID 33304318, 2020). "In diabetic cardiomyopathy, EDV improved cardiac function by upregulating Nrf2 and SIRT1 and potently counteracted heart oxidative injury." (PMID 38285279, 2024). "In diabetic cardiomyopathy, HOTAIR acts as a competing endogenous RNA (ceRNA) to increase SIRT1 expression by sponging miR-34a24." (PMID 38250607, 2024). "Another study showed that resveratrol treatment ameliorated cardiac injuries by regulating the SIRT1/PGC‐1α pathway and oxidative stress reduction in an experimental diabetic cardiomyopathy model." (PMID 39723061, 2024). "Stem cell transplantation restores Sirt-1 and SOD2 expression, resulting in ROS/inflammasome signaling blocking and diabetic cardiomyopathy improvement." (PMID 36354780, 2022). "Sulforaphane was shown to prevent the decreased expression of Sirt1 and Pgc-1α in an animal model of T2DM, as a protective mechanism against diabetic cardiomyopathy and muscle atrophy." (PMID 28386307, 2017). "In addition to blocking GP91, we find that antioxidant proteins, as well as Sirt-1 and SOD2 expression, also play an important role in ameliorating diabetic cardiomyopathy progression through scavenging ROS production." (PMID 36354780, 2022). "Based on the increasingly important role of SIRT1 in cardiac disease, SIRT1 activators (resveratrol and SRT1720) have been shown to exert multifunctional protective roles against diabetic cardiomyopathy and other cardiac diseases via antioxidant and anti-inflammatory effects." (PMID 33430144, 2021). "Additionally, resveratrol was found to recruit sarcoplasmic Ca2+ATPase (SERCA2a) in the diabetic hearts by SIRT1-mediated restoration of SERCA2 promoter activity and improves cardiac functions in diabetic cardiomyopathy." (PMID 34071497, 2021).
diabetic cardiomyopathy (continued). "In contrast, the levels of other factors previously reported to act protectively against diabetic cardiomyopathy, including Sirt1, Nampt, and Namnat1, were not significantly changed by the βHB treatment." (PMID 34356388, 2021). "Additionally, Metrnl improves diabetic cardiomyopathy and reduces heart cell damage by inhibiting cGAS/STING signaling through autophagy, but also attenuates adriamycin-induced cardiotoxicity via activation of the cAMP/PKA/SIRT1 pathway." (PMID 40082768, 2025). "Resveratrol, carnosic acid, beta carotene, and curcumin can activate autophagy through the SIRT1/FOXO1/Rab7 axis, PI3K/Akt/mTOR, activate AMPK and JNK1, phosphorylated Bcl-2 and Bim and subsequently disrupted their interactions with Beclin1 to treat diabetic cardiomyopathy." (PMID 37810881, 2023). "Therefore, it is not difficult for us to deduce that AMPK/SIRT1/Nrf2/HO-1/NF-kB Inflammasome Signaling Pathway plays an important role in the anxiety process of diabetic cardiomyopathy." (PMID 35355717, 2022). "Moreover, SIRT1/FOXO/Rab7 has been proposed as a potential therapeutic pathway which mediates the effects of resveratrol on autophagic flux and ameliorates dysfunctional autophagy in diabetic cardiomyopathy." (PMID 33498216, 2021). "In addition, protein sirtuin 1 (SIRT1) activation is known to increase the sarcoplasmic reticulum (SR) calcium ATPase 2 (SERCA2) expression, improving cardiac function in different heart diseases, such as diabetic cardiomyopathy." (PMID 29494535, 2018). "Despite these previous reports, correlation with SIRT1, NADPH oxidase and NF-κB in diabetic cardiomyopathy has not been fully clear." (PMID 33308195, 2020). "In this study, streptozotocin-induced mouse model and high-glucose-treated cell model were conducted to investigate the protective roles of BAK on diabetic cardiomyopathy, in either the presence or absence of SIRT1-specific inhibitor EX527, SIRT1 siRNA, or Nrf2 siRNA." (PMID 33062139, 2020).
ischemic stroke (62 papers, 2016 to 2026). A stroke disorder caused by obstruction of blood flow to the brain, due to thrombotic (local blood clot formation) or embolic (due to a blood clot or other material traveling from another site) event. "Future prospective clinical studies should be designed to explore the expression profiles and activity changes of Sirt1 and its related targets in ischemic stroke, and to identify novel diagnostic and prognostic markers." (PMID 40160465, 2025). "C1q/tumor necrosis factor-related protein-3 (CTRP3) safeguards hippocampal neurons from mitochondrial damage caused by ischemic stroke via the Sirt1/PGC-1α signaling pathway." (PMID 40160465, 2025). "Subsequently, a cohort study focused on evaluating the effects of Sirt1 activator resveratrol on blood pressure, weight status, glucose, and lipid profile which are the main risk factors for ischemic stroke." (PMID 37622049, 2023). "Silent information regulator family protein 1 (SIRT1) is essential for autophagy initiation and has been implicated as a regulator of autophagy in ischemic stroke." (PMID 37915409, 2023). "A study of the localization and expression of SIRT1, 2, 6 and plasticity-associated proteins in the recovery period after ischemic stroke in mice showed that there was an increase in the levels of SIRT1 and SIRT2 during this recovery period." (PMID 35625059, 2022). "Resveratrol induced SIRT1 activation has been shown to downregulate PARP1 activity and attenuate DNA damage, thereby underlining the role of SIRT1 against ischemic stroke." (PMID 32727328, 2021). "Additionally, magnolol causes a downregulation of Ac-FOXO1, induced by the SIRT1 expression, which means that magnolol can also exert a protective effect against ischemic stroke via resistance function against oxidative stress." (PMID 36105479, 2022). "In this study, we provide new insights into the detailed mechanism for the antiapoptotic effect of EA and its ability to suppress neuronal autophagy in the early stage of ischaemic stroke, which might be associated with the SIRT1-JNK and ERK pathway." (PMID 33603645, 2021). "hence, the involvement of Sirt1 is crucial in the process of cellular apoptosis during ischemic stroke." (PMID 40160465, 2025). "The application of transcutaneous electrical acupoint stimulation can effectively suppress neuroinflammation by modulating the Sirt1/NLRP3 signaling pathway following ischemic stroke, thereby mitigating cerebral injury." (PMID 40160465, 2025). "The identification of Sirt1 as a potential therapeutic intervention for ischemic stroke is supported by the data we have collected." (PMID 40160465, 2025). "The natural compound magnoflorine, possessing antioxidant and immunomodulatory properties, has been discovered to exert a preventive effect against ischemic stroke by activating the Sirt1/AMPK pathway in order to inhibit autophagy." (PMID 40160465, 2025). "In summary, the participation of Sirt1 in the neuropathogenesis of ischemic stroke suggests its potential as a therapeutic target for managing this condition." (PMID 40160465, 2025). "Although synthetic drugs such as rosuvastatin and simvastatin exhibit neuroprotective effects in ischemic stroke by activating Sirt1, they remain in the experimental pharmacological phase." (PMID 40160465, 2025). "The efficacy of RSV in the treatment of ischemic stroke has been demonstrated through its ability to enhance the Sirt1/PGC-1α signaling pathway." (PMID 40160465, 2025). "The literature examination revealed the intricate involvement of Sirt1 in regulating both physiological and pathological mechanisms during ischemic stroke." (PMID 40160465, 2025). "In a mouse model of ischemic stroke, the Sirt1/PGC-1α pathway was activated by intranasal delivery of mitochondria, resulting in reduced brain damage." (PMID 40160465, 2025). "Sirt1 has beneficial roles in neuroinflammation-related diseases, such as ischemic stroke, traumatic brain injury, spinal cord injury, AD, and PD." (PMID 40906143, 2025).
ischemic stroke (continued). "Within 4.5 h after ischemic stroke onset, compared with those in the control group, the relative protein levels of SIRT1 and BMAL1 in the peripheral blood decreased, whereas the levels of oxidative stress and inflammation markers increased." (PMID 41440117, 2025). "The findings imply that the inhibition of Sirt1 offers neuroprotection against ischemic stroke by suppressing necroptosis." (PMID 40160465, 2025). "Research has indicated that in the model of ischemic stroke, the Notoginseng triterpenes have been found to regulate the Sirt1/PGC-1α pathway, thereby inhibiting mitochondrial damage." (PMID 40160465, 2025). "Overall, our results suggest that our system can efficiently induce Sirt1, and Sirt1 can regulate other neuroprotective genes to ameliorate the secondary effects of ischemic stroke such as edema." (PMID 39239521, 2024). "Our system specifically targets neuroprotective genes, such as SIRT1, providing a tailored therapeutic approach for ischemic stroke." (PMID 39239521, 2024). "Among the four subgroups, the content of MDA, IL-6, and TNF-α was highest in patients with ischaemic stroke onset from subgroup 2 (06:00–11:59), while the expression levels of SOD, BMAL1, and SIRT1 were lowest in patients with ischaemic stroke in subgroup 2." (PMID 38245621, 2024). "A significant reduction in the expression levels of basic helix–loop–helix ARNT Like 1 (BMAL1) and the transcription regulator of circadian clock genes (SIRT1) was also demonstrated in patients with ischemic stroke from group 2." (PMID 39334896, 2024). "A recent study indicated that quercetin maintained the BBB integrity and inhibiting reactive oxygen species (ROS) generation through activating Sirt1, thereby improving neurological function after ischemic stroke." (PMID 37622049, 2023). "Similar to SRT1720, SRT2104 was also found to efficiently activate Sirt1 to alleviate brain damage after ischemic stroke by regulating microglia polarization." (PMID 37622049, 2023). "Animal and clinical studies have shown that activation of Sirt1 can lessen neurological deficits and reduce the infarcted volume, offering promise for the treatment of ischemic stroke." (PMID 37622049, 2023). "Next, we will discuss the progresses of Sirt1 in animal models and clinical trials of ischemic stroke in recent years." (PMID 37622049, 2023). "During the hyperacute phase of ischemic stroke, researchers observed the suppression of Sirt1 and upregulation of TRFA6 protein and ROS levels were observed." (PMID 37622049, 2023). "It has been discovered that activated Sirt1 exhibits obviously potent neuroprotective effects on ischemic stroke and other neurodegenerative diseases." (PMID 37622049, 2023). "The study revealed that miR-142-3p can modulate neuronal apoptosis after ischemic stroke by targeting Sirt1." (PMID 37622049, 2023). "Recent studies have found that Sirt1 can alleviate ischemic stroke injury, including reducing cerebral infarcted volume and neurological deficits." (PMID 37622049, 2023). "Magnoflorine, a natural compound with anti-oxidant and immunomodulatory effects, has also been found to protect against ischemic stroke by inhibiting autophagy through the activation of the Sirt1/AMPK pathway." (PMID 37622049, 2023). "Studies in animal models and clinical trials have shown that Sirt1 is an efficient treatment for ischemic stroke." (PMID 37622049, 2023). "Its neuroprotective effects against ischemic stroke have been demonstrated, and Sirt1 is considered the most critical node in this process." (PMID 37622049, 2023). "Further studies are needed to elucidate the interaction between Sirt1 and necroptosis following ischemic stroke." (PMID 37622049, 2023). "Sirt1 plays an important role in endogenous neuroprotection against ischemic stroke due to its anti-apoptotic effects." (PMID 37622049, 2023).